LINC00487 (long independently transcribed non-coding RNA 487)
Synonyms: FLJ42418
Gene: Long non-coding RNA gene on chromosome 2 (6,728,177 to 6,782,637, reverse strand). Ensembl gene ENSG00000205837.
Diseases named in the same sentence as LINC00487 in open-access papers:
LINC00487 is named in the same sentence as 5 diseases in open-access papers, as found by Europe PMC text mining. Sharing a sentence is not in itself a finding about the gene and the disease. The quoted sentences say what the papers report.
autoimmune disease (1 paper, 2022). A disorder resulting from loss of function or tissue destruction of an organ or multiple organs, arising from humoral or cellular immune responses of the individual to their own tissue constituents. "In particular, LINC00487 was found to be up-regulated in B cells derived from patients with primary Sjögren’s syndrome which is defined as an autoimmune disease." (PMID 35163455, 2022).
B-cell Lymphoma (1 paper, 2025). "Key genes such as PAK3, LINC00487, AID, PURPL, and BCL2 were among the most dysregulated, highlighting TIMAP’s role in critical oncogenic pathways in B-cell Lymphoma." (PMID 41170526, 2025).
diffuse large B-cell lymphoma (1 paper, 2020). "Further, LINC00487 expression is upregulated in the subgroup of diffuse large B cell lymphoma with molecular characteristics of germinal centre B cells, compared with other subgroups, and is associated with the efficacy of B cell depletion therapy." (PMID 32571405, 2020).
squamous cell carcinoma of the lung (1 paper, 2022). "Furthermore, LINC00487 appears to be particularly up-regulated in squamous cell carcinoma of the lung." (PMID 35163455, 2022).
LINC00487 also shares sentences with these, for which no sentence is quoted: primary Sjögren’s syndrome (1 paper).